HNRNPA1L3 (heterogeneous nuclear ribonucleoprotein A1 like 3)
Synonyms: HNRNPA1P48
Gene: Protein-coding gene on chromosome 16 (51,553,436 to 51,647,132, forward strand). Ensembl gene ENSG00000224578.
Subcellular location (Human Protein Atlas): Nucleoplasm
Gene Ontology:
Molecular function: mRNA 3'-UTR binding; nucleic acid binding; RNA binding
Biological process: mRNA splicing, via spliceosome
Cellular component: nucleoplasm; catalytic step 2 spliceosome; nucleus
Genetic constraint (gnomAD): Loss-of-function variants: 3 observed, 7.44 expected, observed/expected ratio (o/e) 0.4, 90% interval 0.18 to 1.04. That is too few expected variants to judge how well the gene tolerates losing a copy. Missense variants: 187 observed, 180.31 expected, observed/expected ratio (o/e) 1.04, 90% interval 0.92 to 1.17. Synonymous variants: 76 observed, 61.7 expected, observed/expected ratio (o/e) 1.23, 90% interval 1.02 to 1.49.
Homologues: Orthologues: zebrafish hnrnpa1b (74% identical). Paralogues in human: HNRNPA1 (99% identical), HNRNPA1L2 (96% identical), HNRNPA3 (80% identical), HNRNPA2B1 (67% identical), HNRNPA0 (40% identical), HNRNPD (34% identical), MSI2 (33% identical), MSI1 (32% identical), HNRNPDL (31% identical), DAZAP1 (31% identical), HNRNPAB (30% identical), NUCLEOLIN (30% identical), and 24 more.